NOTCH3 (notch receptor 3)
Diseases named in the same sentence as NOTCH3 in open-access papers (continued):
Sharing a sentence is not in itself a finding about the gene and the disease.
glioma (31 papers, 2013 to 2025). A benign or malignant brain and spinal cord tumor that arises from glial cells (astrocytes, oligodendrocytes, ependymal cells). "In gliomas, NOTCH3 overexpression has been associated with the promotion of glioma cell proliferation and therapeutic resistance, suggesting a conserved oncogenic role across diverse tumor types." (PMID 40502769, 2025). "Studies have shown that NOTCH3 gene polymorphisms have the potential to be diagnostic and therapeutic biomarkers for gliomas." (PMID 36382054, 2022). "We demonstrated for the first time that ASAP3 and NOTCH3 are substantially associated in human glioma samples." (PMID 36382054, 2022). "For example, higher expression of Achaete-Scute Family BHLH Transcription Factor-1 (ASCL1), DLL1, Notch1, Notch3, Notch4, and Hey1 is associated with high-grade glioma and a worse prognosis." (PMID 36643842, 2021). "Our analysis suggested that Notch signaling pathway (including key genes METTL3, DLL3, HES1, and NOTCH3) closely implicated with tumorigenesis and cancer development was found to be involved in glioma." (PMID 34589481, 2021). "In the present study, we studied the association between the NOTCH3 gene polymorphism and the clinical feature and prognosis of gliomas in Chinese patients." (PMID 25738469, 2015). "We found that the 684G>A polymorphism affects the tumor NOTCH3 expression level and is closely associated with a higher tumor grade, poorer tumor differentiation, and karnofsky performance score in these glioma patients." (PMID 25738469, 2015). "We observed that loss of NOTCH3 significantly suppressed colony formation of glioma cells on soft agar." (PMID 24143218, 2013). "The results demonstrated that GBM patients with high expression of Notch3 indicated a shorter survival period, which was similar to the previous reports that Notch3 gene polymorphism is associated with the prognosis of gliomas." (PMID 37284062, 2023). "Therefore, ASAP3 and NOTCH3 are interconnected with each other and associated with the development of adult glioma." (PMID 36382054, 2022). "We found that NOTCH3 684G>A polymorphism is the only one that affected the prognosis of gliomas." (PMID 25738469, 2015). "Our study indicates that the NOTCH3 gene 684G>A polymorphism may be used as a prognosis marker for gliomas." (PMID 25738469, 2015). "Although the role of NOTCH3 in gliomas has been reported, however, little is known about the relation between NOTCH3 gene polymorphisms and the clinical feature as well as the prognosis of glioma patients." (PMID 25738469, 2015). "Since NOTCH3 knockdown resulted in growth suppression of glioma cells, we further investigated the underlying molecular mechanism related to this growth inhibition by analyzing cell cycle and apoptosis following inhibition of NOTCH3 activity." (PMID 24143218, 2013). "Downregulation of CCND1 leads to accumulation of a subset of glioma cells at G0/G1 which might be the underlying mechanism of low proliferative capabilities of glioma cells upon silencing of NOTCH3." (PMID 24143218, 2013). "Overall, SIRT6 inhibits glioma cell proliferation, migration, and invasion through the negative regulation of NOTCH3." (PMID 40710366, 2025). "CHAC, typically downregulated in GBM cell lines, was identified as a key gene up-regulated by TMZ treatment, enhancing glioma apoptotic death and inhibiting Notch3-mediated pathways." (PMID 39874307, 2025). "CHAC1 is identified as a critical mediator in the cytotoxic effects of temozolomide (TMZ) on glioma cells, particularly through its interaction with the Notch3 pathway." (PMID 39534397, 2024). "This inhibition is crucial as it reduces the activation of Notch3’s intracellular domain (NICD), leading to decreased Notch3-mediated signaling pathways that are typically involved in glioma cell survival and proliferation." (PMID 39534397, 2024). "The proliferative role of Notch3 in GBM was validated in U251/U87 glioma cells by Western blot and immunostaining." (PMID 37284062, 2023).
glioma (continued). "The results demonstrated that Notch3 knockdown significantly reduced the propagation of glioma cells, suggesting that Notch3-mediated GBM progression is closely related to tumor cell proliferation." (PMID 37284062, 2023). "Notch 3 was also reported to be activated in glioma and played a significant role in glioma cell proliferation, cell migration, invasion, and apoptosis based on the in vitro experiment." (PMID 37284062, 2023). "According to the results of our study, further analysis of ASAP3 and NOTCH3 co-expression in survival analysis in adult gliomas." (PMID 36382054, 2022). "In univariate survival analysis, Age, tumor location, local recurrence, tumor resection, WHO grade, Ki-67 expression, ATRX expression, ASAP3 expression, and NOTCH3 expression were the significant prognostic factors for PFS in adult gliomas." (PMID 36382054, 2022). "We intend to investigate the biological function of ASAP3 and its closely related protein NOTCH3, as well as provide new hints for molecularly targeted glioma therapy, by elucidating the expression and clinical significance of ASAP3 in adult glioma." (PMID 36382054, 2022). "NOTCH3 promotes glioma cell invasion and proliferation through activation of cell cycle protein D1 (CCND1) and EGFR gene expression." (PMID 36382054, 2022). "Glioma treatment research is now focused on trying to gain a better understanding of the precise processes that are involved in the NOTCH3 pathway." (PMID 36382054, 2022). "We analyzed the relationship between the expression of ASAP3 and NOTCH3 and the clinicopathological parameters of 211 adult gliomas using TMA." (PMID 36382054, 2022). "Immunohistochemistry was used to detect the protein expression of ASAP3, NOTCH3, and their relationship with clinicopathological features in all cohorts in order to study the potential function of ASAP3 and NOTCH3 in the progression of adult glioma." (PMID 36382054, 2022). "Multivariate prognostic analysis showed that age, tumor site, WHO grade, recurrence, Ki-67 expression, IDH1 mutant, ATRX, ASAP3, and NOTCH3 expression were shown to be independent predictive determinants of overall survival in gliomas." (PMID 36382054, 2022). "Based on database comparison and literature assessment, the role of the relationship between ASAP3 and NOTCH3 in glioma has attracted the research group's interest among the 21 ASAP3 interacting proteins evaluated in the NOTCH signaling pathway." (PMID 36382054, 2022). "KMT2A has an epigenetic regulation role on NOTCH1 and NOTCH3, and this mechanism is essential for inhibiting glioma proliferation." (PMID 33711952, 2021). "For example, Alqudah MA elucidated that via activation of CCND1 and EGFR, NOTCH3 promotes glioma cell proliferation, migration and invasion." (PMID 33676540, 2021). "Notch-2, on the other hand, was identified as a prognostic marker for glioma along with Notch-3, which also promotes glioma cell proliferation." (PMID 32290213, 2020). "There are several members in the NOTCH family (NOTHC1-4, of which NOTCH3 in more important in glioma formation." (PMID 25738469, 2015). "However, the gene polymorphism of NOTCH3 in gliomas prognosis remains unknown." (PMID 25738469, 2015). "We found that the 684G>A polymorphism affects the tumor NOTCH3 expression level and is closely associated with a higher tumor grade, poorer tumor differentiation, and KPS scores in these gliomas patients." (PMID 25738469, 2015). "Recent studies show that NOTCH3 is involved in the glioma development and it is also a prognostic factor for glioma patients." (PMID 25738469, 2015). "Our objective is to determine the molecular roles of NOTCH3 in glioma pathogenesis and aggressiveness." (PMID 24143218, 2013). "Following copy number analysis of the most significantly deregulated genes mapped to chromosome 19, we found NOTCH3 locus (19p13.12) as one of the most significant amplification in 17% of glioma biopsies." (PMID 24143218, 2013).
glioma (continued). "Using quantitative real time PCR, we assessed NOTCH3 transcript levels in glioma biopsies and found that NOTCH3 RNA levels were significantly higher in tumor vs. non tumor specimens." (PMID 24143218, 2013). "Our results elucidate for the first time the pivotal role of NOTCH3 knockdown in suppression of glioma cell proliferation and invasion, arrest of cell cycle and induction of apoptosis." (PMID 24143218, 2013). "In our glioma population, detailed genomic analysis of chromosome 19 amplifications revealed NOTCH3 as one of the most significant amplification." (PMID 24143218, 2013). "In the present study, we explored the oncogenic role of NOTCH3 in malignant glioma by downregulating NOTCH3 expression in glioma cell lines using shRNA." (PMID 24143218, 2013). "We found that loss of NOTCH3 inhibits glioma cell migration and invasion and demonstrated that NOTCH3 regulates glioma cell invasion via interaction with the EGFR/PI3K/AKT signaling pathway because NOTCH3 Knockdown indeed reduced the expression of EGFR." (PMID 24143218, 2013). "We suspect that NOTCH3 is a critical element in glioma based on the frequency of gain of chromosome 19 and amplification of NOTCH3 locus (19p13.12) and its positive association with worst patients’ outcomes." (PMID 24143218, 2013). "Together, these findings suggest that NOTCH3 is highly likely to induce glioma cell invasion and proliferation via at least the activation of CCND1, cMYC and EGFR gene expression." (PMID 24143218, 2013). "Here we show for the first time that NOTCH3 plays a major role in glioma cell proliferation, cell migration, invasion and apoptosis." (PMID 24143218, 2013). "In the current study, we found that NOTCH3 was significantly overexpressed in a subset of high grade gliomas at both the mRNA and protein levels." (PMID 24143218, 2013). "Using quantitative real time PCR, RT-PCR and immunobloting, we further analyzed the level of NOTCH3 expression and confirmed that NOTCH3 was amplified in several glioma biopsies." (PMID 24143218, 2013). "Our findings elucidate, for the first time, the ability of NOTCH3 to alter aggressive behavior of glioma cells such as proliferation and invasion." (PMID 24143218, 2013). "In particular, we report anti-glioma effect of NOTCH3 knockdown similar to that previously reported about silencing of NOTCH1." (PMID 24143218, 2013). "Some bioinformatics studies have also revealed that high expression of METTL3 in glioma tissues can activate multiple oncogenic pathways and upregulate the expression of oncogenic factors, including those in the Notch pathway and NOTCH3, thereby promoting the onset of gliomas." (PMID 40469294, 2025). "In adult glioma, the high expression of NOTCH3 is related to the overexpression of ASAP3." (PMID 36382054, 2022). "NOTCH3 amplified is associated with worse survival compared to tumors with non-amplified locus for gliomas in Chinese patients." (PMID 36382054, 2022). "ASAP3 may be combined with EGFR to arouse NOTCH3 expression to promote adult glioma proliferation and invasion." (PMID 36382054, 2022). "Although it has been reported that the expression of ASAP3 is elevated in glioma, its prognostic value and relationship with the expression of the cooperative protein NOTCH3 remain unclear." (PMID 36382054, 2022). "It is well known that Notch3 activation promotes invasive glioma formation." (PMID 35053843, 2022). "NOTCH3 is a NOTCH family member that promotes glioma proliferation and invasion." (PMID 36382054, 2022). "We speculated that ASAP3, as an upstream factor of the NOTCH3 signaling pathway, may promote glioma proliferation by regulating the expression of NOTCH3, thus affecting the development and prognosis of glioma." (PMID 36382054, 2022).
glioma (continued). "Our studies showed that high NOTCH3 expression in adult gliomas was related to several factors, including gender, recurrence, tumor resection by surgery or resection, postoperative radio-chemotherapy, higher WHO grade, Ki-67 expression ≥10%, and ATRX expression." (PMID 36382054, 2022). "Therefore, ASAP3 and NOTCH3 as oncogene factors have the potential to be prognostic biomarkers and therapeutic targets in adult glioma." (PMID 36382054, 2022). "METTL3 can activate Notch pathway and facilitate glioma occurrence through regulating its direct targets NOTCH3, DLL3, and HES1, and Notch pathway genes may serve as the potential treatment targets for glioma." (PMID 34589481, 2021). "Activation of Notch3 causes invasive glioma formation in the optic nerve but has no confirmed effect on GBM." (PMID 36643842, 2021). "We analyzed the clinical characteristics of glioma patients based on their NOTCH3 genotypes." (PMID 25738469, 2015). "Together, these results strongly indicate the anti-apoptotic effect of NOTCH3 in glioma may occur at least via modulation of EGFR." (PMID 24143218, 2013). "Therefore, our study uncovers the prognostic value and the oncogenic function of NOTCH3 in gliomagenesis and supports NOTCH3 as a promising target of therapy in high grade glioma." (PMID 24143218, 2013). "In addition, we used immunoblot to compare NOTCH3 protein expression in glioma patient biopsies clustered according to chromosome 19 status." (PMID 24143218, 2013). "Based on previous results, we hypothesized that NOTCH3 may promote glioma cell migration and invasion." (PMID 24143218, 2013). "The Notch signaling pathway comprises four receptors: Notch1, which may function as either a tumor suppressor or oncogene; Notch2, considered a prognostic marker in glioma; Notch3, which promotes glioma cell proliferation; and Notch4, associated with increased tumor aggressiveness." (PMID 40942013, 2025). "Inhibiting ASAP3 and NOTCH3 co-expression may improve the prognosis of glioma patients." (PMID 36382054, 2022). "The high expression of ASAP3 and NOTCH3 could predict the short OS in adult glioma." (PMID 36382054, 2022). "From other findings and our cell experiment results, we demonstrated that METTL3 can activate Notch pathway and facilitate glioma occurrence through regulating its direct targets NOTCH3, DLL3, and HES1, and Notch pathway genes may serve as the potential treatment targets for glioma." (PMID 34589481, 2021). "Collectively, these findings and other previous report demonstrated that METTL3 can activate Notch pathway and facilitate glioma occurrence through regulating its direct targets NOTCH3, DLL3, and HES1, and Notch pathway genes may serve as the potential treatment targets for glioma." (PMID 34589481, 2021). "Two hundred and eighty targets were upregulated or downregulated in 14 cancer types, among which BAX, CENPK, DLL3, and NOTCH3 showed a consistent upregulation in multiple cancers and glioma, indicating that these genes may play a carcinogenic role in a variety of cancers." (PMID 34589481, 2021). "Therefore, we hypothesized that NOTCH3 may induce cell invasion in glioma based on similar oncogenic roles." (PMID 24143218, 2013). "Inhibition of NOTCH3 resulted in significant decrease of glioma cell survival and this effect of growth suppression was maintained to the extent that we were not able to create stable cell lines that express NOTCH3 shRNA since the cells died 2–3 weeks following NOTCH3 knockdown." (PMID 24143218, 2013). "Nuclear-localized SIRT6 is notably downregulated in glioma and acts as a tumor suppressor through various mechanisms, including inhibition of the JAK2/STAT3 and NOTCH3 signaling pathways." (PMID 40710366, 2025). "In glioma cells, CHAC1 can bind to Notch3 protein and inhibit its activation under temozolomide induction, leading to inactivation of Notch3-mediated downstream signaling pathways." (PMID 35372041, 2022).
glioma (continued). "The following prognostic factors influence the OS in adult glioma: Age, tumor location, local recurrence, tumor resection, WHO grade, Ki-67 expression, ATRX expression, ASAP3 expression, and NOTCH3 expression." (PMID 36382054, 2022). "Therefore, ASAP3 and NOTCH3 may be the potential biomarkers of poor prognosis in adult glioma." (PMID 36382054, 2022). "The expression of ASAP3 was an independent prognostic factor for the OS of glioma, and the expression of ASAP3 was positively correlated with that of NOTCH3 and Ki-67 expression rate." (PMID 36382054, 2022). "Another effect of TMZ‐induced upregulation of CHAC1 expression in glioma cells is the binding of CHAC1 to the NOTCH3 protein and consequent inhibition of NOTCH3 activation, resulting in attenuation of NOTCH3‐mediated pathways." (PMID 29316219, 2018). "Seventeen genes represent active Notch signaling components, including NOTCH1, NOTCH3, HES1, MAML1, DLL-3, and JAG2, which are enriched in the proneural subtype of glioma stem cells." (PMID 26599017, 2015). "Additionally, CHAC1 inhibits the Notch3 signaling pathway by binding to Notch3 and preventing its activation, which further contributes to TMZ’s cytotoxic effects on glioma cells." (PMID 39534397, 2024). "Thus, CHAC1 acts as a suppressor of Notch3, enhancing the apoptotic and cytotoxic effects of TMZ on glioma cells." (PMID 39534397, 2024). "Importantly, we found a positive correlation between A3C and glioma stem cell marker genes such as CD133, SOX2, Notch3, CD44, and CXCR4 was noted." (PMID 37809064, 2023). "Meanwhile, ASAP3 and NOTCH3 co-expression correlated with poorer OS and PFS in glioma patients." (PMID 36382054, 2022). "We constructed univariate and multivariate analyses of OS and PFS in adult glioma patients so that we could evaluate the clinical characteristics of these patients and the prognostic significance of the expression of the ASAP3 and NOTCH3 proteins." (PMID 36382054, 2022). "In adult glioma, we explore the effects of ASAP3 and NOTCH3 and their relationships on prognosis." (PMID 36382054, 2022). "METTL3 was positively associated with DLL3, HES1, and NOTCH3 expressions in the CGGA glioma dataset, but not the GSE16011 glioma dataset (0.23 < cor < 0.34, p < 0.05)." (PMID 34589481, 2021). "Moreover, TMZ‐induced upregulation of CHAC1 expression in glioma cells results in the binding of CHAC1 to the NOTCH3 protein and consequent inhibition of NOTCH3 activation, resulting in attenuation of NOTCH3‐mediated pathways." (PMID 29316219, 2018). "As expected, NOTCH3 protein levels were significantly higher in NOTCH3 locus amplified biopsies than their non-amplified locus glioma counterparts." (PMID 24143218, 2013). "The anti-proliferative effects of NOTCH3 knockdown in glioma cells extended to in vitro assays of tumorigenicity, in which glioma cells lacking NOTCH3, were not able to proliferate independently of external signals, as confirmed in soft agar colony formation." (PMID 24143218, 2013). "This modulatory effect of NOTCH3 can be predominantly attributed to NOTCH target genes as well as its potential cooperation with major aberrant signaling pathways in malignant glioma such as EGFR, C-MYC and CCND1, which are all often altered in glioma." (PMID 24143218, 2013). "However, due to the single experimental method in this study, the mechanism of ASAP3 in glioma through regulation of the NOTCH3 signaling pathway needs to be further verified at the cellular level and in animal models so as to further confirm the mechanism of ASAP3 in glioma." (PMID 36382054, 2022). "Patients with high NOTCH3 expression showed substantially shorter PFS and OS than patients with low NOTCH3 expression, indicating that it may emerge as a crucial driver for the malignant development of glioma in a univariate prognostic analysis." (PMID 36382054, 2022).